PLG (plasminogen)
Diseases named in the same sentence as PLG in open-access papers (continued):
Sharing a sentence is not in itself a finding about the gene and the disease.
subarachnoid haemorrhage (2 papers, 2013 to 2014). "Therapeutic trials in vasospasm related to inflammation in subarachnoid haemorrhage in humans showed a reduction of vasospasm through calcium antagonists, endothelin receptor antagonists, statins, and plasminogen activators." (PMID 25610703, 2014).
T-cell lymphoma (2 papers, 2022 to 2024). "When we compared three groups of B-cell lymphoma, T-cell lymphoma, and healthy dogs, the serum β2M (p=0.006), clusterin (p=0.01), immunoglobulin (Ig) heavy chain V region GOM (p=0.02), and plasminogen (p=0.02) were significantly higher in B-cell than T-cell lymphoma." (PMID 35765478, 2022). "When compared between B- and T-cell lymphomas, B-cell phenotypes had upregulated immunoglobulin (Ig) heavy chain V region GOM (p=0.02), clusterin (p=0.01), apolipoprotein C1 (APOC1, p=0.05), and plasminogen (p=0.02)." (PMID 35765478, 2022). "In neoplastic B phenotypes, drastically differential increased protein levels were observed in Ig heavy chain V region GOM, clusterin, β2M, and plasminogen, while APOC1 was only notably elevated in T-cell lymphoma." (PMID 35765478, 2022).
abdominal aortic aneurysm (1 paper, 2021). Enlargement and ballooning of the vessel that supplies arterial blood to the abdomen, pelvis and legs. "For example, the plasminogen/MMP-9 cascade is a promising target for regulating inflammatory responses and development of abdominal aortic aneurysms (AAAs)." (PMID 34769032, 2021).
acute myeloid leukaemia (1 paper, 2017). "Therefore, the relevant up-regulation of SAA1 and down-regulation of plasminogen may be due to the direct effect of these disturbed signalling pathways, and can be used for the diagnosis of acute myeloid leukaemia in future." (PMID 29180721, 2017).
acute respiratory distress syndrome (1 paper, 2022). Progressive and life-threatening pulmonary distress in the absence of an underlying pulmonary condition, usually following major trauma or surgery. "However, inhalation of fibrinolytic agents such as tPA and plasminogen can reduce the risk of bleeding much more than systemic administration and may improve acute respiratory distress syndrome (ARDS) by dissolving fibrin clots in and near the alveolar spaces." (PMID 35328761, 2022).
adenoma (1 paper, 1998). A neoplasm arising from the epithelium. "Plasminogen activation and tissue-type activator levels were lower in adenomas than in mucosae (P < 0.001)." (PMID 9461001, 1998).
age-related macular degeneration (1 paper, 2016). Age-related loss of vision in the central portion of the retina (macula), secondary to retinal degeneration. "The 8 known pQTLs along with the kallikrein pQTL are associated with a variety of phenotypes, including age-related macular degeneration (C3b), activated partial thromboplastin times (F12), serum metabolites (KLKB1), binding of LBP to lipopolysaccharide (LBP), and plasma plasminogen levels (LP(a))." (PMID 27329291, 2016).
Airway obstruction (1 paper, 2024). Obstruction of conducting airways of the lung. "A 22-month-old male diagnosed with PLGD-1 at four weeks of age with difficult-to-treat LC and a plasminogen activity level <2% experienced respiratory complications so severe that he suffered cardiopulmonary arrest due to airway obstruction." (PMID 39372655, 2024). "Urgent, short-term, or long-term treatment with systemic plasminogen replacement therapy may be needed when treating airway obstruction resulting from fibrinous lesions." (PMID 39372655, 2024).
allergic asthma (1 paper, 2022). A asthma with a basis in a pathological type I hypersensitivity reaction. "To our knowledge, we are the first to confirm that probiotic and pathogenic GAPDH may share similar functions in adhering to host plasminogen, but they have distinct immunomodulatory activities in allergic asthma depending on their respective dehydrogenase activities." (PMID 36175886, 2022).
Alport syndrome (1 paper, 2016). A rare renal disease characterized by glomerular nephropathy with hematuria progressing to end-stage renal disease (ESRD), frequently associated with sensorineural deafness, and occasionally with ocular anomalies. "Although not specifically investigated in Alport syndrome, in vitro keratinocyte cell migration towards fibronectin was documented to be stimulated by plasminogen and plasmin by a MMP-9 dependent mechanism and cooperatively interacting with β1 integrins." (PMID 26942026, 2016).
aneurysm (1 paper, 2021). Bulging or ballooning in an area of an artery secondary to arterial wall weakening. "Interestingly, the plasminogen-urokinase-plasmin axis seems to be critically involved in aneurysm formation, placing a certain emphasis on elastin breakdown products, such as collagen XIII and endostatin." (PMID 34778850, 2021).
anthrax infection (1 paper, 2011). An infection caused by Bacillus anthracis bacteria. "However, B. anthracis protease InhA can accelerate the uPA-mediated plasminogen activation, thereby suggesting a mechanism of plasmin modulation in anthrax infection." (PMID 21464960, 2011).
aortic aneurysm (1 paper, 2024). A ruptured aneurysm located in the wall of the proximal portion of the descending aorta proceeding from the arch of the aorta. "Nevertheless, in subjects with aortic aneurysm, Glu1-plasminogen activation of fibrinolysis was disturbed in the mechanism of lysine side-chain carbonylation in the fibrinogen sequence." (PMID 38965130, 2024).
aortic valve calcification (1 paper, 2024). "Another potential mechanism involves Lp(a) promoting thrombosis by competing with plasminogen and inhibiting plasmin from dissolving fibrous clots, which could result in fibrin deposition and aortic valve calcification." (PMID 39457433, 2024).
Autoimmunity (1 paper, 2015). The occurrence of an immune reaction against the organism's own cells or tissues. "Our findings and those of others suggest that plasminogen-/- mice would be more susceptible to injury-induced autoimmunity." (PMID 26132730, 2015).
babesiosis (1 paper, 2017). Babesiosis refers to a condition caused by microscopic parasites that infect the red blood cells. "The current study found lower plasminogen activity in dogs with babesiosis at admission compared to activity on day 6 (P = 0.011)." (PMID 28363279, 2017). "Dogs with babesiosis also had increased concentrations of TM, ICAM-1 and HMGB-1 and decreased plasminogen and PAI-1 at presentation compared to day 6 after treatment." (PMID 28363279, 2017). "Decreased plasminogen activity and lower concentrations of both fibrinolysis inhibitors at admission (PAI-1 and TAFI in complicated cases) might result from increased consumption and lead to increased fibrinolytic activity due to the procoagulant state in babesiosis." (PMID 28363279, 2017).
bacterial meningitis (1 paper, 2022). Inflammation of the membranes surrounding the brain and spinal cord due to a bacterial infection. "SPN uses surface receptors to bind host plasminogen, a protease able to cleave BM components and plasminogen activation products are found in the CSF during bacterial meningitis and correlate strongly with BBB permeability." (PMID 36683708, 2022).
Bovine mastitis (1 paper, 2009). INFLAMMATION of the UDDER in cows. "Interestingly, induction of plasminogen metabolism has been used as an indication of virulence of S. uberis associated with bovine mastitis." (PMID 19925655, 2009).
brain cancer (1 paper, 2022). A primary or metastatic malignant neoplasm affecting the brain. "Plasminogen activation plays an important role in the invasion and metastasis of lung, breast and brain cancer." (PMID 34861103, 2022). "PLG plays an important role in the invasion and metastasis of lung, breast, and brain cancer." (PMID 34861103, 2022).
C1 inhibitor deficiency (1 paper, 2025). "Moreover, the genetic search only included the 2 main genetic variants of HAE without C1-inhibitor deficiency, the factor XII and plasminogen variants." (PMID 40151541, 2025).
Candida infections (1 paper, 2021). "Although inhibiting plasminogen activation by uPA is considered as a therapeutic target for invasive bacterial infection, more investigations are needed to establish the role of uPA and plasminogen in Candida infections." (PMID 34512620, 2021).
Candidemia (1 paper, 2020). A form of invasive candidiasis where species of CANDIDA are present in the blood. "We further discovered that mAb 12D9 which targets to Eno1 could prevent host plasminogen being captured by C. albicans and was effective for controlling candidemia in vivo." (PMID 33115324, 2020).
cardiac arrest (1 paper, 2022). Cessation of breathing and/or cardiac function. "Just as in trauma, hypoperfusion, the activation of protein C, and the initiation of the plasminogen pathway of fibrinolysis manifest themselves in the HF of cardiac arrest." (PMID 36555922, 2022).
cardiac hypertrophy (1 paper, 2020). "Moreover, severe injury such as cardiac hypertrophy is displayed, which indicates the involvement of several DRGs of IL6, LUM, LRG1, PLG, with other molecules such as Alpha actinin, PDGF, Tgf beta, and TLR2 and TLR4." (PMID 32753925, 2020).
cerebral infarction (1 paper, 2025). An ischemic condition of the brain, producing a persistent focal neurological deficit in the area of distribution of the cerebral arteries. "In this study, we identify and characterize a novel compound heterozygous PLG mutation clinically associated with cerebral infarction." (PMID 41398600, 2025). "This study identifies a novel compound heterozygous PLG mutation (p.Ala620Thr/p.Gly568Arg) as the molecular basis for type II deficiency-associated cerebral infarction." (PMID 41398600, 2025).
cerebral malaria (1 paper, 2022). A sequestration of Plasmodium falciparum in the brain, which can cause coma and/or seizures. "The expression of the membranous form of urokinase plasminogen activator receptor (uPAR) has been associated with lesions during cerebral malaria suggesting a role of molecules implicated in the plasminogen activation pathway in cerebral malaria including suPAR." (PMID 35204613, 2022).
cholangiocarcinoma (1 paper, 2024). A carcinoma that arises from the intrahepatic biliary tree (intrahepatic cholangiocarcinoma) or from the junction, or adjacent to the junction, of the right and left hepatic ducts (hilar cholangiocarcinoma). "Our radar plots revealed that F3, SERPINC1, F2, PLG, and PLAT exhibited the highest positive correlation with TMB in uterine carcinosarcoma (UCS), cholangiocarcinoma (CHOL), CHOL, thymoma (THYM) and LGG, respectively." (PMID 39179711, 2024).
chronic kidney disease (1 paper, 2025). Impairment of the renal function secondary to chronic kidney damage persisting for three or more months. "Continuous exposure to excessive transglomerular passage of plasminogen in glomerular injury acts as a “second hit” to glomerular disease, causing progression of chronic kidney disease independent of the initial injury." (PMID 40576805, 2025).
chronic liver failure (1 paper, 2022). Liver failure that develops slowly and gradually for some time, possibly for years, often as the result of cirrhosis, or malnutrition. "As anticipated, reduced levels of plasminogen, plasmin inhibitor, thrombin activatable fibrinolysis inhibitor (TAFI), and factor XIII are found in both acute and chronic liver failure." (PMID 35446468, 2022).
chronic obstructive pulmonary disease (1 paper, 2021). A chronic and progressive lung disorder characterized by the loss of elasticity of the bronchial tree and the air sacs, destruction of the air sacs wall, thickening of the bronchial wall, and mucous accumulation in the bronchial tree. "Vitamin D binding protein in chronic obstructive pulmonary disease and, similar to our findings, plasminogen has been found down-regulated in the plasma of patients with IPF." (PMID 34424905, 2021).
chronic otitis media (1 paper, 2023). Chronic form of otitis media (disease). "It is however worth to note that plasminogen or uPA-deficient mice in the course of life spontaneously develop chronic otitis media with extensive fibrin deposition in middle ear cavity, which may also contribute to delay of TM healing." (PMID 36810718, 2023).
chronic thromboembolic pulmonary hypertension (1 paper, 2018). Chronic thromboembolic pulmonary hypertension (CTEPH) is characterized by the persistence of thromboemboli in the form of organized tissue obstructing the pulmonary arteries. "And high plasma fibrinogen and low plasminogen are associated with poor survival in the chronic thromboembolic pulmonary hypertension (CTEPH) patients." (PMID 30410637, 2018).
clear cell renal cell carcinoma (1 paper, 2025). "Another study demonstrated that targeting the PLG receptor S100A10 suppresses angiogenesis in clear cell renal cell carcinoma (ccRCC), proving that PLG inhibition may represent a promising therapeutic strategy to impede tumor progression in ccRCC." (PMID 40396123, 2025).
colitis (1 paper, 2023). Inflammation of the colon. "Considering these data, we suggest that inhibition of the plasminogen-plasmin system may contribute to amelioration of DSS-induced colitis in mice." (PMID 36806262, 2023).
corneal opacities (1 paper, 2024). "In the genetic examination, the suspected variant genes of this child associated with corneal opacities include SLC4A11 and PLG." (PMID 39669368, 2024).
corneal ulceration (1 paper, 2025). "The plasminogen/PA system in corneal ulceration and wound healing is largely reviewed." (PMID 41471311, 2025).
crescentic glomerulonephritis (1 paper, 2023). A histopathologic term for a pattern of diseases characterized by extensive crescent formation in the glomeruli; patients present clinically with rapid deterioration of renal function, and possible progression to end-stage renal failure within weeks or months. "Experimental studies have also demonstrated the participation of the plasminogen/plasmin system and that plasmin/plasminogen activators have a protective effect against renal injury in crescentic glomerulonephritis." (PMID 38001978, 2023).
cryptococcosis (1 paper, 2012). An acute or chronic, localized or disseminated infection by Cryptococcus neoformans. "The ability of C. neoformans to modulate PA expression in primary cells and use PA activity for enhanced virulence suggest that fungal subversion of the plasminogen system may contribute to invasive cryptococcosis." (PMID 23145170, 2012). "However, given that our BBB model incorporates key physiological effectors and parameters of plasminogen regulation, cryptococcal ability to fundamentally alter host PA expression in this system could indicate that similar pathogen-host interactions occur during cryptococcosis." (PMID 23145170, 2012).
deficiencies (1 paper, 2024). "From those, PLG/K19E and PLG/A601T are examples of two relatively abundant PLG variants that have been associated with PLG deficiencies (PD), but their pathogenic mechanisms are unclear." (PMID 38984351, 2024). "Studying the effects of single amino acid substitutions in PLG that lead to clinical outcomes, as found in congenital PLG deficiencies, also presents a convenient informational source that can provide critical insights into its role in vivo." (PMID 38984351, 2024). "An important finding resulting from case studies of heterozygous relatives of congenital PLG deficiency patients is that PLG activity and PLG antigen concentration can be significantly lower than that considered to be normal, with individuals appearing healthy." (PMID 38984351, 2024). "Since IEF changes may reveal alterations of the PLG structure, the IEF pattern adds valuable information for a phenotypic characterization of a PLG variant in a patient and a first step towards a diagnosis of a PLG deficiency." (PMID 38984351, 2024).
dementia (1 paper, 2024). Loss of intellectual abilities interfering with an individual's social and occupational functions. "Despite this, we do not know if defects in the plasminogen/plasmin system are also associated with dementia in other non‐AD pathologies and, therefore, unrelated to the accumulation of Aβ in neurons." (PMID 38386354, 2024).
Dengue hemorrhagic fever (1 paper, 2024). A serious condition caused by Dengue virus infection. "Similarly, another study indicated that in dengue hemorrhagic fever, prolonged APTT may result from the secretion of dengue virus nonstructural protein 1 (NS 1), which inhibits plasminogen activation." (PMID 39995828, 2024).
Disseminated intravascular coagulation (1 paper, 2017). Disseminated intravascular coagulation is characterized by the widespread activation of coagulation, which results in the intravascular formation of fibrin and ultimately thrombotic occlusion of small and midsize vessels. "The plasma plasminogen, FDP, and D-dimer levels were elevated after 2 hours, and those of uPA, tPA, and PAI-1 exhibited marked changes, indicating disseminated intravascular coagulation (DIC)." (PMID 28744465, 2017).
Down syndrome (1 paper, 2018). "The plasminogen activating system has an impact on the condition of neurons and neurites in Down syndrome." (PMID 29342922, 2018). "Diminished activity of tPA in Down syndrome brain converts less plasminogen to plasmin; this produces less proNGF to activate NGF." (PMID 29342922, 2018). "In this review, we describe mechanisms of proteolytic enzymes (MMP-9 and plasminogen activation system), their role in Down syndrome, their inhibition by EGCG, possible degradation of this polyphenol and the ability of EGCG and its degradation products to cross the blood–brain barrier." (PMID 29342922, 2018).
Duchenne muscular dystrophy (1 paper, 2012). Duchenne muscular dystrophy (DMD) is a neuromuscular disease characterized by rapidly progressive muscle weakness and wasting due to degeneration of skeletal, smooth and cardiac muscle. "It was important to analyze if the α-enolase/plasminogen axis might be functional in a muscular disease context, such as Duchenne muscular dystrophy (DMD), which courses with persistent tissue degeneration and fibrosis." (PMID 23239981, 2012).
endometriosis (1 paper, 2014). The growth of functional endometrial tissue in anatomic sites outside the uterine body. "A previous study examined activation of TGF-β in women with endometriosis via the plasminogen activation pathway that was found to be increased at sites of endometriosis lesions." (PMID 25207642, 2014).
endotoxemia (1 paper, 2024). "For example, in a mouse model of endotoxemia, the observed decline in lung-associated TFPI activity was prevented in plasminogen knockout mice." (PMID 39624584, 2024).
Fabry disease (1 paper, 2014). Fabry disease (FD) is a progressive, inherited, multisystemic lysosomal storage disease characterized by specific neurological, cutaneous, renal, cardiovascular, cochleo-vestibular and cerebrovascular manifestations. "Moreover, it has been demonstrated that in subjects with Fabry disease, both plasminogen, plasmin and alpha-2-antiplasmin levels are elevated, and its secondary decrease is due to overconsumption of these factors." (PMID 24959362, 2014).
frontotemporal lobar degeneration (1 paper, 2024). "Considering that tauopathy is extensively involved in different neurodegenerative diseases, including PD, AD, frontotemporal lobar degeneration and Pick’s disease, these findings further suggest the therapeutic potential of plasminogen in these diseases." (PMID 38615036, 2024).
gastric adenocarcinoma (1 paper, 2021). "Gastric adenocarcinoma (GAC); Long non-coding RNA (lncRNA); lncRNA TRPM2 antisense RNA (TRPM2-AS); Plasminogen Activator, Urokinase (PLAU); Wild-type (WT); mutant (MUT)." (PMID 34696681, 2021).
giant cell arteritis (1 paper, 2024). "These signals belonged to five different loci, two of which are established risk loci for giant cell arteritis, 6p21.32 (HLA-DQA1, rs41269974; p=1·60 × 10–87; OR 2·03 [95% CI 1·90–2·17]) and 6q26 (PLG, rs4252114; p=1·38 × 10–13; OR 1·25 [1·18–1·32])." (PMID 38734017, 2024).